EGF (epidermal growth factor)
Diseases named in the same sentence as EGF in open-access papers (continued):
Sharing a sentence is not in itself a finding about the gene and the disease.
cutaneous leishmaniasis (2 papers, 2018 to 2025). Leishmaniasis affecting the skin. "According to the deficiency of EGF in cutaneous leishmaniasis, in the present study, intra- and perilesional administration of exogenous recombinant EGF in combination with the antileishmanial drugs synergistically contributed to accelerating the healing of CL." (PMID 39808642, 2025). "In the healing process of cutaneous leishmaniasis caused by L. braziliensis, a higher expression of TGFβ1 was more associated with acute infection and failure or relapses after treatment, and the higher levels of EGF were associated with adequate wound healing." (PMID 39808642, 2025). "Nevertheless, more studies are required to investigate the effect of exogenous EGF on the wound healing process, the anti-inflammatory response, and scar formation in cutaneous leishmaniasis." (PMID 39808642, 2025). "A recent study investigated expression levels of EGF in different stages of cutaneous leishmaniasis and upon the treatment." (PMID 39808642, 2025). "Further studies are needed to explore the beneficial effect of combining EGF with antileishmanial drugs in patients with cutaneous leishmaniasis." (PMID 39808642, 2025). "Further studies are warranted to explore the beneficial effects of combining EGF with antileishmanial drugs in patients with cutaneous leishmaniasis in order to accelerate wound healing and reduce the scar." (PMID 39808642, 2025). "Consistently, our study showed that the simultaneous application of exogenous recombinant EGF and antileishmanial drugs improved the healing of cutaneous leishmaniasis." (PMID 39808642, 2025).
demyelinating disease (2 papers, 2022 to 2025). A broad group of disorders that affect the myelin sheaths that cover the neurons. "Several studies have shown that epidermal growth factor (EGF) acts as a remyelinating stimulator by promoting the differentiation of oligodendrocyte precursor cells (OPCs) in myelinating oligodendrocytes (OLs), which could be favorable for its application in the treatment of demyelinating diseases." (PMID 35330085, 2022).
endometrial tumor (2 papers, 2016). "Taken as a whole, from the view of the cancer microenvironment, an up-regulation of NMU signaling in progressive endometrial tumor cells would also help these malignant cells become more sensitive to niche growth factors such as EGF and TGFβ via the adhesion signaling-SRC cascades." (PMID 26849234, 2016).
esophageal tumor (2 papers, 2022 to 2025). "We speculate that EGF likely upregulates the expression of apoptosis-related genes downstream of the IFN-γ/STAT1 pathway, thereby facilitating the apoptosis of esophageal tumor cells." (PMID 40909948, 2025).
Ewing sarcoma (2 papers, 2015 to 2022). A small round cell tumor that lacks morphologic, immunohistochemical, and electron microscopic evidence of neuroectodermal differentiation. "Other important growth factor signaling pathways upregulated in Ewing Sarcoma include members of the EGF, FGF and Ephrin families, which share downstream molecular machinery, namely MAPK and PI3K signaling cascades, with the IGF pathway." (PMID 25603314, 2015).
follicular thyroid cancer (2 papers, 2013 to 2022). "We have previously demonstrated that human follicular thyroid cancer cells, when cultured in Space, grow in the form of extraordinary large three-dimensional aggregates with altered expression of EGF and CTGF genes." (PMID 24244418, 2013). "The EGF gene expression was clearly upregulated in AD and MCS of FTC-133 follicular thyroid cancer cells in space during the Shenzhou-8 space mission." (PMID 35252204, 2022).
gastric adenocarcinoma (2 papers, 2021 to 2022). "BC, egg, or EGF alone or in combination with trypsin inhibitors were tested for proliferative (Alamar blue) activity using human gastric adenocarcinoma (AGS) cells, prior to and after incubation with HCl/pepsin and trypsin/chymotrypsin." (PMID 34132332, 2021).
graft versus host disease (2 papers, 2008 to 2021). An immune system disorder that occurs after allogeneic hematopoietic stem cell transplant and is a reaction of donor immune cells against host tissues. "There are also characteristic salivary changes in case of graft-versus-host disease including the elevated concentration of total protein, albumin, EGF, IgG, and a decreased amount of IgA and IgM in the saliva." (PMID 19424479, 2008).
hematoma (2 papers, 2019 to 2022). A hematoma is a collection of blood from a vascular structure into an extravascular space. "ANG-2, EGF, Endoglin, and CXCL4 expression were higher in HUVECs treated with hematoma-derived exosomes (EX-Hematoma group) compared to those treated with serum-derived exosomes (EX-Serum group)." (PMID 31841443, 2019). "Of the growth factors EGF, Granulocyte-macrophage colony-stimulating factor (GM-CSF), and PDGF-BB, only GM-CSF showed increased release in non-smokers’ hematomas when compared to smokers’ hematomas." (PMID 35621464, 2022).
hepatoblastoma (2 papers, 2024). Hepatoblastoma (HB) is a malignant hepatic tumor and is the most common pediatric liver cancer. "Intriguingly, embryonal and fetal tumor organoids are sensitive to FGFR and EGFR inhibitors, respectively, indicating a dependency on EGF/FGF signaling in hepatoblastoma tumorigenesis." (PMID 39567475, 2024). "For the majority of the hepatoblastoma tumoroids (6 of 9 tested), colony formation was abolished in the absence of the standard growth factors usually included in the media (EGF, FGF10, and HGF) or in the presence of a MEK inhibitor, U0126." (PMID 39567523, 2024). "Overall, these findings suggest a previously unrecognized dependency on EGF and FGF signaling pathways in the tumorigenesis of hepatoblastoma." (PMID 39567475, 2024).
hyperplasia (2 papers, 2022). An abnormal increase in the number of cells in an organ or a tissue with consequent enlargement. "Hyperplasia is induced by growth factors such as TGFβ, epidermal growth factor (EGF), and platelet derived growth factor, as well as stimulation by contractile agonists such as histamine and leukotriene D4." (PMID 36277199, 2022). "Leukocyte-derived cytokines, including TNF-α, were reported to be potent inducers of epidermal growth factors (EGF) and receptor (EGFR), which attributed to epidermal hyperplasia and thickening in chronic skin disorders." (PMID 36204219, 2022).
immune deficiency (2 papers, 2019). "Genes related to metabolism (e.g., carbon metabolism) were largely downregulated, whereas upregulated genes mainly encoded multiple components of epidermal growth factor (EGF), insulin, Notch, Toll, and immune deficiency (IMD) signal transduction." (PMID 30914968, 2019).
inflammatory skin disease (2 papers, 2024 to 2025). Inflammatory skin disorders covers a broad category that includes many conditions ranging in severity, from mild itching to grave medical health complications These disorders are common in people of all ages and races. "Since the treatment of mouse skin with IAP and caspase inhibitors can induce TNF-α-dependent skin inflammatory diseases, we further analysed the effect of EGF on this model system." (PMID 38789573, 2024).
insomnia (2 papers, 2022 to 2023). A sleep disorder characterized by difficulty in falling asleep and/or remaining asleep. "In the results, HP, FGA, FGG, FGB, and MMP9 were upregulated in patients with insomnia, and FN1, APP, EGF, AHSG, and IGF1 were downregulated compared with controls." (PMID 35958162, 2022). "The 10 key DEPs screened may be potential targets for insomnia, especially FN1, EGF, HP, and IGF1." (PMID 35958162, 2022).
large cell carcinoma (2 papers, 1989 to 2018). A malignant epithelial neoplasm composed of large, atypical cells. "EGF was demonstrated in all tumour types and every squamous and large cell carcinoma was positive for the antibody." (PMID 2544220, 1989).
laryngeal carcinoma (2 papers, 2016 to 2025). Carcinoma that arises from the laryngeal epithelium. "In addition, FAK contributes to the activation of the EGF signaling pathway and is significantly correlated with an increased risk of laryngeal cancer development and recurrence." (PMID 40735032, 2025). "In addition, β-Elemen can suppress the expressions of VEGF, basic fibroblast growth factor (bFGF), and epidermal growth factor (EGF), and exhibit anti-cancer ability on laryngeal cancer cells both in vitro and in vivo." (PMID 28119606, 2016).
microcephaly (2 papers, 2021). A congenital or acquired developmental disorder in which the circumference of the head is smaller than normal for the person's age and sex. "Conversely, ZIKV-exposed participants without microcephaly displayed a general trend to decrease concentrations of inflammation mediators as IL-2, IL-4, IL-12p40, IL-12p70, TNF-α, TNF-β, IFN-γ, and the growth factors GCSF and EGF." (PMID 33875756, 2021).
myelogenous leukemia (2 papers, 2014 to 2019). "Overexpression of MGAT3 in HeLaS3 cells enhanced the epidermal growth factor (EGF) mediated cell signaling, and transfecting myelogenous leukemia cell line K562 with MGAT3 protected it from natural killer cytotoxicity and increased spleen colonization." (PMID 24516574, 2014). "Furthermore, γ-T3 also abrogated the NF-κB activation by TNFα, phorbol myristate acetate (PMA), okadaic acid, lipopolysaccharide (LPS), cigarette smoke condensate (CSC), IL-1β, and epidermal growth factor (EGF) in human myeloid leukaemia KBM-5 cells." (PMID 30845769, 2019).
myopic macular degeneration (2 papers, 2021 to 2025). "The amount of intraocular EGF was significantly higher in the highly myopic group than in the non-highly myopic group (89.1 ± 40.8 pg versus 34.1 ± 13.2 pg; P = 0.005), and it was highest in the eye with myopic maculopathy (135 pg)." (PMID 34050811, 2021). "The intraocular EGF amount was significantly higher in the highly myopic group than in the non-highly myopic group (89.1 ± 40.8 pg versus 34.1 ± 13.2 pg; P = 0.005 (Mann–Whitney test)), and it was highest in the eye with myopic maculopathy (135 pg)." (PMID 34050811, 2021).
neutropenia (2 papers, 2019 to 2024). A decrease in the number of neutrophils found in the blood. "For instance, chemotherapy-induced neutropenia and epidermal growth-factor inhibitor-related acneiform rash both occur within weeks of treatment initiation, thereby providing information prior to efficacy assessment." (PMID 38690281, 2024).
oral cavity carcinoma (2 papers, 2010 to 2021). A carcinoma arising in the oral cavity. "The lower EGF concentration in the saliva of pre-surgery patients and its growing tendency after surgery may suggest an important role for this factor in oral cavity carcinoma development as well as in the healing of oral mucosa." (PMID 20429940, 2010).
orofacial cleft (2 papers, 2014 to 2023). A disorder of facial skeleton that is characterized by cleft lip and/or cleft palate that result in feeding, speech and hearing problems caused by failures during development. "On the one hand, mice deficient for the TGF-α receptor gene Egfr show an increased incidence of orofacial clefts, and on the other hand, excess EGF inhibits the fusion of cultured mouse palatal shelves." (PMID 25360592, 2014).
osteonecrosis (2 papers, 2021 to 2024). A none disease characterized by death of bone tissue due to a lack of blood supply. "EGF affects processes that are associated with bone healing in the case of surgically induced osteonecrosis of the femoral head (ONFH) by osteoblast differentiation and bone resorption." (PMID 39458926, 2024). "recently found that EGF can promote bone formation and microvascularization in osteonecrosis surgically induced in rats." (PMID 34504500, 2021).
papillary renal cell carcinoma (2 papers, 2019 to 2022). A rare subtype of renal cell carcinoma, arising from the renal tubular epithelium and showing a papillary growth pattern, which typically manifests with hematuria, flank pain, palpable abdominal mass or nonspecific symptoms, such as fatigue, weight loss or fever. "A 3-mRNA signature consisting of ERG, RRM2, and EGF was constructed to predict survival in papillary renal cell cancer with satisfactory accuracy." (PMID 31886185, 2019).
parasitic infection (2 papers, 2014 to 2023). "Production of AREG, EGF, FGF-2, and IGFBP-3 was significantly higher in the intestinal mucosa of colitic mice with parasitic infection than in the intestine of mice without induced disease but infected with H. polygyrus." (PMID 36836678, 2023).
Peptic ulcer (2 papers, 2015 to 2022). The term peptic ulcer refers to acid peptic injury of the digestive tract, resulting in mucosal break reaching the submucosa. "EGF and EGFR protein expression is involved in the re-epithelialization and peptic ulcer healing process, which is associated with the proliferation, differentiation and migration of gastric mucous surface epithelial cells." (PMID 25452787, 2015).
pituitary tumor (2 papers, 2017). A benign or malignant neoplasm affecting the pituitary gland. "Research using human pituitary adenomas and some invasive pituitary tumors has revealed expression of EGF and/or EGFR." (PMID 29255445, 2017). "Here, we summarize what is known about the major stem cell signaling pathways (i.e., NOTCH, WNT, EMT, SHH, Hippo, and epidermal growth factor-EGF/FGF) in pituitary tumors, and where investigations have been conducted, in the candidate TSC populations." (PMID 29255445, 2017). "The past few years have brought considerable progress in the knowledge of molecular changes in ACTH-secreting pituitary tumors, e.g., the involvement of epidermal growth factor and orphan nuclear receptor TR4, differing miRNA patterns, and, lately, also the presence of somatic mutations." (PMID 27220856, 2017). "Upregulated gene expression of cognate receptors of these growth factors, i.e., EGFR, FGFR1, and FGFR3, was detected in the human pituitary tumor SP, suggesting that EGF/FGF signaling may function to drive cell proliferation in these candidate TSC." (PMID 29255445, 2017).
pneumonitis (2 papers, 2018 to 2022). An inflammatory process affecting the lung parenchyma. "One month after the patient restarted treatment with CIMAvax-EGF alone (coincidentally, this is approximately 2 months after the last fraction of radiation treatment), patient #5 developed grade 3 pneumonitis due to radiation requiring oxygen supplementation and steroids." (PMID 35992783, 2022). "Patient #5 continued maintenance dosing while on steroid taper and did not experience recurrent pneumonitis symptoms off steroids despite ongoing treatment with CIMAvax-EGF." (PMID 35992783, 2022).
polyp (2 papers, 2015 to 2020). A usually exophytic mass attached to the underlying tissue by a broad base or a thin stalk. "The aim of the current study was therefore to investigate the effect of EGF on mucin MUC5AC expression and define the involvement of PI3K and TMEM16A in mediating the EGF-induced MUC5AC expression in primary nasal epithelial cell cultures derived from polyp tissue of CRSwNP patients." (PMID 32514271, 2020).
proliferative diabetic retinopathy (2 papers, 2020 to 2023). Advanced retinopathy due to diabetes mellitus characterized by the formation of new vessels in the retina. "Although EGF levels were also measured in the vitreous fluid of patients with proliferative diabetic retinopathy, the levels were very low or below the detection limit of the assay." (PMID 31936869, 2020). "Previous studies indicate an autocrine/paracrine role for EGF, TGF-α, HB-EGF, and EGFR in proliferative diabetic retinopathy." (PMID 37936170, 2023).
prostate adenocarcinoma (2 papers, 2017). "Human prostatic adenocarcinoma cells and skin epidermal cells that are subjected to epidermal growth factor‐induced transformation show reduced colony formation upon loss of PAK2." (PMID 28707321, 2017).
pulmonary mucoepidermoid carcinoma (2 papers, 2021). A lung carcinoma characterized by the presence of malignant non-keratinizing squamoid cells, mucin-producing cells and intermediate type cells. "It was found that chrysin inhibited MUC5AC mucin generation and gene expression in a human pulmonary mucoepidermoid carcinoma cell line (NCI-H292) which is exposed to phorbol 12-myristate 13-acetate (PMA) or epidermal growth factor (EGF)." (PMID 33858433, 2021). "In vitro: EGF (25 ng/mL) or PMA (10 ng/mL) treated NCI-H292 cells (the human pulmonary mucoepidermoid carcinoma cell line)." (PMID 33912050, 2021).
relapsing remitting MS (2 papers, 2014). "However, prolonged exposure to EGF induces oxidative neuronal death and astrocyte commitment from NSCs and a higher secretion of EGF has been demonstrated in PBMCs of patients with relapsing remitting MS (RR-MS)." (PMID 25047180, 2014).
renal dysfunction (2 papers, 2018 to 2019). "We observed that increased urinary secretion of MCP-1 and IL-6 in HHTg rats was accompanied by decreased urinary secretion of EGF, another promising marker of early renal dysfunction." (PMID 31886287, 2019). "Although it was not possible to differentiate EGF and DGF using TIC, differences between early and late groups point to blood shunting in renal dysfunction." (PMID 30537946, 2018).
respiratory failure (2 papers, 2021 to 2024). The significant impairment of gas exchange within the lungs resulting in hypoxia, hypercarbia, or both, to the extent that organ tissue perfusion is severely compromised. "Respiratory failure was signified by depression of EGF, GZMA, LAP, IL-4, and IL-7, and increased expression of MUC-16, ARG-1, and LAMP-3." (PMID 34177897, 2021). "This is supported by unique associations between COVID-19 and high concentrations of growth factors implicated in IPF pathogenesis (EGF, PDGF-AB/BB, PDGF-AB/BB, FLT-3L, TGF-α), as well as close relationships between TGF-α, severe COVID-19, and related respiratory failure." (PMID 38368384, 2024).
salivary gland carcinoma (2 papers, 2014 to 2023). A carcinoma that arises from the major or minor salivary glands. "Some researchers suggested that molecular targeted chemotherapy including an anti-HER2 or anti-epidermal growth factor (EGFR)-based regimen might be the most promising strategy for treatment of salivary gland cancers." (PMID 24475740, 2014).
sarcopenia (2 papers, 2025). Progressive decline in muscle mass due to aging which results in decreased functional capacity of muscles. "Applying MTA-MO to multi-omics data identified seven potential hub genes associated with sarcopenia: ESR1, ATM, CDC42, EP300, PIK3CA, EGF, and PTK2B." (PMID 41303670, 2025). "Using the MTA‐MO method, we identified 639 gene targets, and by analysing PPIs and querying public databases, we narrowed this list down to seven potential hub genes associated with sarcopenia (ESR1, ATM, CDC42, EP300, PIK3CA, EGF and PTK2B)." (PMID 40045692, 2025).
skin toxicities (2 papers, 2020 to 2021). "In a previous study, we demonstrated that EGF ointment is effective at managing EGFR inhibitor-related skin toxicities and improves patients’ QoL, compared with placebo, via a placebo-controlled, double-blind, multicenter, pilot phase III trial." (PMID 33113881, 2020). "In our prior study, we demonstrated that recombinant human epidermal growth factor (rhEGF) treatment is effective for managing epidermal growth factor receptor inhibitors (EGFRIs)-related skin toxicities and improves patients’ quality of life (QoL) compared with placebo." (PMID 33113881, 2020).